TRIML2 (tripartite motif family like 2)
Synonyms: SPRYD6; FLJ25801
Tractability: Antibody: the Human Protein Atlas places it where antibodies can reach. PROTAC: ubiquitination databases record sites on it.
Gene: Protein-coding gene on chromosome 4 (188,091,247 to 188,109,611, reverse strand). Ensembl gene ENSG00000179046.
Subcellular location (Human Protein Atlas): Cytosol; Plasma membrane
Gene Ontology:
Molecular function: identical protein binding; protein binding; ubiquitin protein ligase activity; zinc ion binding
Biological process: innate immune response; protein ubiquitination
Cellular component: cytoplasm
Genetic constraint (gnomAD): Loss-of-function variants: 25 observed, 29.78 expected, observed/expected ratio (o/e) 0.84, 90% interval 0.61 to 1.17. The upper end of that interval is the gene's LOEUF score, 1.17, which puts it in group 5 of 6, group 1 being the genes least tolerant of losing a copy. Missense variants: 536 observed, 549.46 expected, observed/expected ratio (o/e) 0.98, 90% interval 0.91 to 1.05. Synonymous variants: 187 observed, 208.05 expected, observed/expected ratio (o/e) 0.9, 90% interval 0.8 to 1.01.
Homologues: Orthologues: chimpanzee TRIML2 (98% identical), macaque TRIML2 (91% identical), pig TRIML2 (64% identical), rabbit TRIML2 (63% identical), dog TRIML2 (62% identical), guinea pig TRIML2 (61% identical), mouse Triml2 (57% identical), rat Triml2 (56% identical). Paralogues in human: TRIML1 (35% identical), TRIM21 (31% identical), TRIM58 (29% identical), TRIM11 (29% identical), TRIM39 (29% identical), TRIM27 (27% identical), TRIM4 (25% identical), TRIM41 (24% identical), TRIM69 (24% identical), TRIM17 (24% identical), TRIM7 (24% identical), TRIM75 (23% identical), and 68 more.
Diseases named in the same sentence as TRIML2 in open-access papers:
TRIML2 is named in the same sentence as 12 diseases in open-access papers, as found by Europe PMC text mining. Sharing a sentence is not in itself a finding about the gene and the disease. The quoted sentences say what the papers report.
oral squamous cell carcinoma (2 papers, 2022 to 2023). "Indeed, TRIML2 silencing has been shown to decrease cellular proliferation and induce cell cycle arrest at the G1 phase in human oral squamous cell carcinoma." (PMID 37516854, 2023). "Previous studies have shown TRIML2 knockdown oral squamous cell carcinoma (OSCC) cells showed decreased cellular proliferation by cell-cycle arrest at G1 phase and TRIML2 might play a significant role in tumoral growth." (PMID 36685979, 2022).
oral cancer (1 paper, 2020). "Therefore, the authors concluded that the expression status of TRIML2 might be an indicator of OSCC progression and resveratrol may be a potential new therapeutic drug for oral cancer therapy via TRIML2." (PMID 32486484, 2020).
prostate carcinoma (1 paper, 2024). A carcinoma that arises from epithelial cells of the prostate gland. "Under these conditions, several SNPs were detected near genes (LINC01824, TRIML2, and RPS2P25) by GWAS that may be associated with the development of prostate cancer." (PMID 38406143, 2024).
stomach cancer (1 paper, 2025). "Ultimately, we confirmed via laboratory testing that suppressing TRIML2 hinders the growth and infiltration of stomach cancer cells." (PMID 41000398, 2025). "Ultimately, in vitro investigations were used to confirm the functional significance of TRIML2 in the advancement of gastric cancer." (PMID 41000398, 2025). "Finally, in vitro experiments revealed that TRIML2 knockdown inhibited the proliferation and migration of gastric cancer cells." (PMID 41000398, 2025). "Initially, we created stable cell lines in vitro by suppressing the expression of TRIML2 in MKN45 and HGC27 gastric cancer cell lines." (PMID 41000398, 2025). "The newly constructed RCDRI consisted of four Regulated cell death-related genes (CD36, SERPINE1, TRIML2, and GRP) and has been shown to be an effective predictive marker for the survival of gastric cancer patients and was trained with multiple external datasets." (PMID 41000398, 2025).
triple-negative breast carcinoma (1 paper, 2022). An invasive breast carcinoma which is negative for expression of estrogen receptor (ER), progesterone receptor (PR), and human epidermal growth factor receptor 2 (HER2). "TRIML2 was significantly associated with prognosis, with a higher expression in triple-negative breast cancer cell lines than in normal mammary cell lines." (PMID 35565484, 2022).
viral infection (1 paper, 2020). "However, only TRIML2 is induced in human choriocarcinoma cell line JEG3 with poly(I:C) treatment to simulate inflammation during viral infection." (PMID 31633784, 2020).
tumor (5 papers, 2018 to 2026). "Using a mouse model of metastatic TNBC, we identified four new CTC surface markers, AHNAK2, CAVIN1, ODR4, and TRIML2, which specifically stain tumor cells." (PMID 41543394, 2026). "The risk heatmap indicates that TRIML2, CAMK2N1, and DKK1 were upregulated in the high-risk cluster, suggesting their tumor-promoting role." (PMID 36685979, 2022). "Among other targets, type-I interferon promotes the tumor suppressor TRIML2, which also elicits antiviral and antibacterial activities; it participates in the correct development of macrophages and in the expression of nitric oxide and of the major histocompatibility complex II to present antigens." (PMID 35562916, 2022).
cancer (2 papers, 2022). A tumor composed of atypical neoplastic, often pleomorphic cells that invade other tissues. "One cancer-associated gene (MPHOSPH8) was upregulated in samples infected with M.BCG relative to those infected with P.BCG, whereas three genes were downregulated in M.BCG (MIR31HG, SAA1, and TRIML2)." (PMID 35562916, 2022).
infection (2 papers, 2018 to 2022). The state of being infected such as from the introduction of a foreign agent such as serum, vaccine, antigenic substance or organism. "Overall, the differential expression of MPHOSPH8, MIR31HG, SAA1 and TRIML2 could show us the subtle changes that occur in the infection between M.BCG and P.BCG." (PMID 35562916, 2022). "In the permissive cells Mrc5 and Vero with primary infection of HCMV and HSV1, respectively, we observed that the protein level of STAT6 was gradually inhibited along with the increase expression of lytic genes (IE1/2 in HCMV, ICP0 in HSV1), while ubiquitylated TRIML2 was enhanced." (PMID 30532138, 2018).
TRIML2 also shares sentences with these, for which no sentence is quoted: Alzheimer disease (1 paper); breast carcinoma (1); lymphoma (1).